MMP9 (matrix metallopeptidase 9)
Diseases named in the same sentence as MMP9 in open-access papers (continued):
Sharing a sentence is not in itself a finding about the gene and the disease.
breast carcinoma (continued). "Within the NF-κB signaling, p65/p50 is known to directly bind to the MMP9 promoter’s NF-κB response element, playing an essential role in controlling MMP9 expression in breast cancer." (PMID 38653973, 2024). "In contrast to control cells, TSP50 knockdown breast cancer cells showed significantly increased E-cadherin protein level and significantly decreased MMP9, Slug and Snail protein levels." (PMID 39030572, 2024). "Altogether, these results suggest that the H3K36 dimethylation plays a crucial role in MMP-9 gene regulation in breast cancer cells, induced by TGF-β/TNF-α co-stimulation." (PMID 39351229, 2024). "In MDA-MB-231 breast cancer cells, it inhibits cancer cell invasion, migration, adhesion, and reduces the activity of matrix metalloproteinase-9 (MMP-9), thereby suppressing breast cancer cell proliferation, invasion, and metastasis." (PMID 38962006, 2024). "Consistently, SAMD5 overexpression markedly reduced Ki67, MMP2, and MMP9 protein levels in breast cancer cells relative to the control group." (PMID 39524172, 2024). "This study investigates the impact of lidocaine (combined with sevoflurane or propofol anesthesia ) during breast cancer surgery inhibits the expression of biomarkers associated with metastasis and recurrence (specifically H3Cit, NE, MPO, MMP-9 and VEGF-A)." (PMID 38678209, 2024). "One study evaluated the effect of curcumin treatment on MMP-2 and MMP-9 gene expression in a breast cancer cell line (MDA-MB-231)." (PMID 39335164, 2024). "We further demonstrate that TGF-β priming and Smad2/3 signaling drive synergy with TNF-α to promote MMP-9 expression in breast cancer cells." (PMID 39351229, 2024). "Despite the recognized importance of MMP-9 in breast cancer progression, the regulatory mechanisms governing its expression within the TME remain incompletely understood." (PMID 39351229, 2024). "It has been demonstrated that overexpression of MMP-2 or MMP-9 led to induction of EMT in breast cancer." (PMID 38539165, 2024). "For this purpose, we investigated CCL7, CCR5, RhoJ, and MMP9 expression in different breast cancer cells: MCF7, MDA-MB-231, MDA-MB-361, ZR751, BT549, and TD47D by using HME1 as a control." (PMID 38247865, 2024). "Our results show that inhibition of histone methylation by BIX 01294 attenuated the synergistic effect of TGF-β/TNF-α co-stimulation on MMP-9 expression in MDA-MB-231 breast cancer cells." (PMID 39351229, 2024). "The effect of CHI3L1 on reducing E-cadherin expression and simultaneously increasing MMP-9 was demonstrated in a study of breast cancer cells by Scully and colleagues." (PMID 39399677, 2024). "It reduces the production of proteins linked to metastasis, such as MMP-2 and MMP-9, in the MCF-7 breast cancer cell line." (PMID 38672151, 2024). "We found that combined treatment of TGF-β/TNF-α synergistically upregulates the production of MMP-9 by the MCF-7 breast cancer cell line." (PMID 39351229, 2024). "Inhibition of MMP9 expression in colorectal cancer cells and reduction of cell migration and invasion in breast cancer cells have been documented following treatment with ASP extracts." (PMID 39697544, 2024). "In summary, our research unveils a novel mechanism wherein GATA4 curtails breast cancer cell metastasis by downregulating MMP9 expression, suggesting a potential therapeutic avenue for breast cancer metastasis." (PMID 38653973, 2024). "Specifically, the expression and activity of MMP9 hold significant relevance to breast cancer metastasis and tumor malignancy, and elevated MMP9 levels increased the malignancy of breast tumor." (PMID 38653973, 2024). "In particular, cyanidin-3-O-sambubioside and delphinidin lowered the expression of phospho-Akt or blocked the MAPK signaling pathway, inducing a decrease in MMP-9 and leading to the inhibition of the metastatic processes in breast cancer cells." (PMID 38540096, 2024).
breast carcinoma (continued). "In breast cancer, tumor cells were reported to induce MMP9 expression in fibroblasts through Smad, Ras, MAPK, and PI3-kinase pathways in models in vitro of co-culture of tumor cells and fibroblasts." (PMID 38606999, 2024). "SRC‐1 and Ets2 interact to regulate expression of MMP9 target genes in Aromatase inhibitors resistance in breast cancer cells." (PMID 38506084, 2024). "Fisetin inhibits cell migration in mammary carcinoma by silencing the gene regulatory protein Nrf2 in the nuclear fraction, leading to reduced activity of MMP-9 and MMP-2." (PMID 38611849, 2024). "First, Kleppel-like factor-9 (KLF9) can recruit HDAC1 to reduce the level of acetylation at the binding site of KLF9 to the matrix metallopeptidase 9 (MMP9) promoter, thereby inhibiting the invasion and migration of breast cancer cells." (PMID 38584203, 2024). "Our insights into the unique molecular interplay of the GATA4/NF-κB/MMP9 pathway shed new light on potential therapeutic avenues for breast cancer." (PMID 38653973, 2024). "The preceding results have exposed that LDBK, through B1R, provokes the release of MMP2 and MMP9 in breast cancer cells, which are key molecules for extracellular matrix degradation and invasion." (PMID 39519260, 2024). "MMP-9 produced by tumours was reported to promote breast cancer progression, metastasis and angiogenesis." (PMID 39450334, 2024). "In this study, we created a brand-new class of physiologically transformable NPs (MST@PBAS) that perform differently when exposed to overexpressed MMP-9 in the TME of breast cancer." (PMID 39427007, 2024). "In vitro experimental findings have demonstrated the significant impact of MMP-9 and IL-8 on the progression of breast cancer." (PMID 39834817, 2024). "In cultured breast cancer cells, TNF-α, via the induction of the production of MMP-2 and MMP-9 in tumor-associated macrophages (TAMs), can contribute to the invasion of neoplastic cells into surrounding tissues." (PMID 39339184, 2024). "Prior research indicates that the downregulation of LCN2 and MMP-9 can significantly suppress breast cancer migration and invasion." (PMID 39188682, 2024). "Les-6287 reduced the concentration of MMP-2, MMP-9, and ICAM-1, all of which are linked to metastasis and a poor prognosis in breast cancer patients." (PMID 39199694, 2024). "α-Curcumene has been shown to significantly inhibit the migration and invasion of MDA-MB-231 breast cancer cells by suppressing matrix metalloproteinase-9 (MMP-9), demonstrating excellent therapeutic potential in the treatment of breast cancer." (PMID 39338358, 2024). "The interaction of SRC‐1 and Ets2 regulates MMP9 target genes expression in Aromatase inhibitors resistance in breast cancer cells." (PMID 38506084, 2024). "Pterostilbene (10 μM) was also studied by Pan and his team, who demonstrated inhibition of MMP-9 upon treatment of breast cancer cells." (PMID 38540096, 2024). "The capability of breast cancer invasion was reduced because of the MMP-9 level in the microenvironment." (PMID 38589471, 2024). "Silibinin also inhibits cancer cell migration, and MMP-9 expression in thyroid and breast cancer cells is reduced by protecting the ECM." (PMID 38672151, 2024). "The concentrations of MMP-2 and MMP-9 in breast cancer cells declined under treatment with the Les-6287, as well as the doxorubicin." (PMID 39199694, 2024). "In studies conducted on MDA-MB-231 breast cancer cells, Isoginkgetin was found to reduce the production of matrix metalloproteinase MMP-9, Akt, and PI3K." (PMID 39065725, 2024). "Our findings highlight GATA4’s inhibitory on MMP9 and delve into its unique mechanism in counteracting breast cancer invasion and metastasis." (PMID 38653973, 2024). "Increased expression of vimentin and MMP9 can be found in various epithelial cancers, including lung, colorectal, and breast cancer." (PMID 38388902, 2024).
breast carcinoma (continued). "Studies have indicated that EHH can inhibit NF‐κB activity and reduce the expression of TNFα‐induced matrix metalloproteinase (MMP)‐9 mRNA, thereby attenuating the migratory capabilities of breast cancer cells." (PMID 38801409, 2024). "Several studies reported the decrease in invasiveness and MMP-2/MMP-9-mediated migration in several breast cancer cell lines, in a cholangiocarcinoma cell line (30 μM) and in a prostate cancer cell line (>5 μM)." (PMID 38540096, 2024). "For example, MMP9's role as a potential prognostic marker and therapeutic target has been studied and suggested in breast cancer." (PMID 39074261, 2024). "Resveratrol’s anti-metastatic properties were confirmed in mouse breast cancer 4 T1 cells, where it reduced the activity and expression of MMP-9 in a concentration-dependent manner and mitigated cell adhesion, motility, and invasion." (PMID 39335164, 2024). "Resveratrol at a concentration of up to 50 μM also inhibited both MMP-2 and MMP-9 in other breast cancer cell lines." (PMID 39335164, 2024). "The inhibition expression of matrix metalloproteinase as MMP-2 and MMP-9 expression levels in breast cancer tissues correlates with lymph node metastasis, tumor growth, angiogenesis, invasion, and metastasis." (PMID 38673967, 2024). "We investigated the influence of truncated O‐glycan trees, also referred to as Tn antigen, following the inactivation of C1GALT1‐specific chaperone 1 (COSMC) on the general and MMP9‐specific proteolytic processing in MDA‐MB‐231 breast cancer cells." (PMID 39074261, 2024). "Emerging evidence showed that COMP also promoted breast cancer stem cell induction by activating Jagged1-Notch3 signaling, and accelerated breast cancer metastasis by modulating the metabolic process and metalloprotease-9 (MMP-9) secretion." (PMID 38584705, 2024). "It has been described that sorafenib inhibits the expression of extracellular matrix proteins—MMP-1 and MMP-9—and increases the level of the adhesive protein—E-cadherin—in breast cancer cells (MCF-7 and MDA-MB-231)." (PMID 38255833, 2024). "In the MMTV-PyMT model, activated MMP-9 has been shown to facilitate breast cancer cell migration, invasion, and metastasis to lung niche." (PMID 39188682, 2024). "Many studies documented that STAT-3-mediated breast cancer metastasis happens through the upregulation of MMP9 and MMP2 expression." (PMID 38673967, 2024). "MTs can activate AP‐1 and NF‐κB, thereby up‐regulating MMP‐9 and enhancing invasiveness, thus promoting the proliferation of breast cancer cells." (PMID 39676279, 2024). "Lovastatin/mevinolin, present in the P. ostreatus ethanolic extract, inhibited angiogenesis and metastasis through the inhibition of MMP-2 and MMP-9 expression in the 4T1 metastatic breast cancer cell line." (PMID 37373268, 2023). "It inhibits breast cancer cell migration and invasion by suppressing MMP-9 expression and induces apoptotic cell death in triple-negative breast cancer cell lines." (PMID 36817446, 2023). "Exogenous TNF-α has been shown to promote breast cancer cell migration accompanied by an increased secretion of MMP9, as well as upregulate the expression of CD26 and FAP-α in a dose-dependent manner." (PMID 36937451, 2023). "For instance, MMP2 and MMP9 expression levels are restored upon DNA methyltransferase inhibition with 5-aza-2′-deoxycytidine in pancreatic and breast cancer cell lines, respectively." (PMID 38017545, 2023). "According to one study, estradiol induces MMP-9 expression in ERα-positive breast cancer cells via PELP1-mediated membrane-initiated signaling." (PMID 37764733, 2023). "These signaling pathways play key roles in breast cancer development and are especially closely related to the expression and activity of MMP-9." (PMID 38202691, 2023). "Altogether, these findings confirmed that the engineered AuNPs inhibit MMP-9 expression via hsa-miR204-5p upregulation and NF-κBp65 deactivation in human breast cancer cells." (PMID 37372062, 2023).
breast carcinoma (continued). "In colon and MCF-7 and MDA-MB-231 breast cancer cells, this compound caused an increase in MMP-2, MMP-7, and MMP-9 levels as well as cell migration." (PMID 36310188, 2023). "Multiple studies have demonstrated that MMP9 is notably increased in malignant tumors, including colon cancer, gastric cancer, lung cancer, breast cancer, and cervical cancer." (PMID 37671970, 2023). "In various preclinical studies, MMP-9 and fibronectin have been identified as specific imaging biomarkers for breast cancer." (PMID 36978072, 2023). "PTGS2 and MMP9 had the highest amplification rates, with DCRGs amplified in bladder cancer, esophagogastric cancer, ovarian cancer, head and neck cancer, and breast cancer." (PMID 37033970, 2023). "It has been reported that STAT3-mediated breast cancer cell metastasis is associated with the upregulation of vimentin, MMP-2, and MMP-9." (PMID 37836626, 2023). "Significant inhibition of the invasive capacity of human breast cancer cells and ovarian cancer cells in vitro, coupled with a decrease in MMP9 expression has also been observed with everolimus treatment." (PMID 36302993, 2023). "MMP-9 is overexpressed in breast cancer and cleaves components in the extracellular matrix to release VEGF, thereby increasing angiogenesis, among other tumorigenic roles." (PMID 37760470, 2023). "Nevertheless, TGFβ is also involved in the increased expression of MMP-9 in astrocytes and breast cancer cells." (PMID 36830637, 2023). "Previously, we demonstrated that F3 had anti-metastatic activity in breast cancer by reducing the expression of N-cadherin, vimentin, MMP-9, MUC1, Twist, and VEGF, while increasing the expression of E-cadherin." (PMID 37259304, 2023). "The products of HO-1 subsequently result in inhibition of MMP-9 and cell migration in breast cancer cells." (PMID 36831338, 2023). "This study demonstrated that microRNA-204-5p regulates the expression of MMP-9 in breast cancer cells MCF-7." (PMID 37372062, 2023). "It has been shown that NAT1 regulates the function of matrix metalloproteinase 9 (MMP9) in breast cancer cell models and protects from reactive oxygen species (ROS) during the shortage of glucose." (PMID 37469704, 2023). "MMP-9 and fibronectin are both highly expressed in the breast cancer TME; Therefore, our imaging and therapeutic strategy can enable real-time detection of 4T1 breast primary and micro-metastatic lesions and image-guided cancer surgery." (PMID 36978072, 2023). "This is the first report that shows that the engineered AuNPs inhibit MMP-9 expression and production via upregulation of microRNA-204-5p in stimulated human breast cancer cells." (PMID 37372062, 2023). "For instance, extracellular Eno1 recombinant proteins are reported to suppress the metabolic activities of breast cancer cells and act as cytotoxic agents by downregulating Snail, TGFβ, and MMP9." (PMID 38250812, 2023). "MT overexpression is associated with chemoresistance in patients receiving adjuvant therapy after surgery and promotes breast cancer cell invasion by increasing the expression of matrix metalloproteinase-9 (MMP9)." (PMID 37049543, 2023). "Its upregulation has been reported in various cancer types, including prostate and gastric carcinoma, and it was also reported to upregulate MMP9 in breast cancer cells." (PMID 36831393, 2023). "Altogether, these results confirmed that the chemically engineered AuNPs inhibit MMP-9 expression via hsa-miR-204-5p upregulation and NF-κBp65 deactivation in human breast cancer cells." (PMID 37372062, 2023). "The combination of MMP9 inhibition with immune checkpoint inhibition enhanced the efficacy of immunotherapy in mouse models of melanoma and breast cancer." (PMID 37106440, 2023).
breast carcinoma (continued). "The early metastatic circuit can be disrupted by inhibiting active MMP9, and warrant further studies of MMP9-targeted anti-metastatic breast cancer therapy." (PMID 36797662, 2023). "Matrine inhibited breast cancer cell migration by reducing the activation of MMP9/MMP2, P65, VEGFR1 and epidermal growth factor (EGF)." (PMID 36706149, 2023). "Several studies have investigated the association between clinicopathological features of breast cancer with MMP-2, MMP-9, and matrix metallopeptidases − 11 (MMP-11) expression." (PMID 37798646, 2023). "The developed immunoplatform achieved a LOD value of 2.4 pg mL−1 MMP-9, and the method was applied to the determination of endogenous MMP-9 in both cancer cell lysates and serum samples of patients diagnosed with different subtypes of breast cancer." (PMID 36679633, 2023). "In breast cancer, non-invasive detection through urinary biomarkers, such as MMP9, NGAL, CD63, ECM1, MAST4, and Filaggrin, offers insights into disease progression." (PMID 38250812, 2023). "In assays employing MCF-7 breast cancer cells overexpressing MMP-9, the MMP-9-selective N-TIMP-2 was uniquely capable of blocking gelatin degradation and inhibiting cellular migration." (PMID 38074088, 2023). "A clinical study of 48 patients with breast cancer and 13 patients with benign breast disease found that expression levels of MMP-9 mRNA were significantly increased in breast cancer patients compared with patients with benign breast disease." (PMID 37496657, 2023). "For example, ginsenoside Rg1 suppresses the invasion and migration of breast cancer cells mainly via the down-regulation of MMP-9, which is mediated by NF-κB." (PMID 37175113, 2023). "Usually, MMP-9 is closely associated with cell migration and invasion in the cancer process, but CMX can curb the invasive development of breast cancer by inhibiting the activity of MMP-9 and blocking the cell migration process." (PMID 38202691, 2023). "Type I collagen fibers play a vital role in stimulating the expression of MMP-9 in CAFs in breast cancer, thereby facilitating increased migration and metastasis." (PMID 38273859, 2023). "Since ADAM8 expression was reported to elevate the expression and/or activity of matrix-metalloproteinase 9 (MMP9) in breast cancer cells, it seems to be likely that MMP9 hampered the fiber displacement generation of ADAM8-Ctrl cells." (PMID 37287457, 2023). "Knocking down Osx suppresses breast cancer invasion and osteolytic metastasis by downregulating MMP9, MMP13, VEGF, IL-8, and PTHrP, indicating the involvement of Osx in breast cancer invasion, angiogenesis, and bone resorption." (PMID 38041134, 2023). "The upregulation of VEGF and MMPs, especially MMP-9, in breast cancer are well known and are considered responsible for tumor invasion and metastasis." (PMID 37735586, 2023). "It was found to promote cellular senescence in breast cancer, to reduce the expression of MMP-9 and limit the invasion of human glioblastoma and breast cancer cell lines via inhibiting the Ras/Raf-1/ERK/AP-1 pathway." (PMID 37506102, 2023). "Our results also show that increased FAK autophosphorylation was followed by increased expression of beta-catenin and MMP9 in the breast cancer cells when exposed to obese adipocyte-conditioned medium, but not in the MCF10A cells." (PMID 38068928, 2023). "ADAM8 is another proteolytic enzyme which promotes the TEM of breast cancer cells through upregulating MMP9, while ADAM9 facilitates the adhesion of NSCLC cells through upregulating integrin α3β1." (PMID 37190188, 2023). "Further studies should demonstrate the type of breast cancer associated with CCCA, as triple-negative breast cancer is associated with dysregulated PADI3 and MMP9." (PMID 37109551, 2023). "In summary, we propose that six key compounds, luteolin, apigenin, quercetin, kaempferol, ursolic acid, and oleanolic acid, contributed to the development of breast cancer by affecting the MMP9 and PPARG proteins." (PMID 37180727, 2023).